EGFR (epidermal growth factor receptor)
Diseases named in the same sentence as EGFR in open-access papers (continued):
Sharing a sentence is not in itself a finding about the gene and the disease.
tumor (continued). "Further studies should expand to establish a role for EGFR/BRD4/miR-9-5p axis in tumour itself and tumour microenvironment towards the development of better, less toxic and more efficient therapeutics for HPV-infected cancers." (PMID 36333293, 2022). "CD36 prevents angiogenesis in tumor microvascular endothelial cells by binding to TSP-1 and inducing apoptosis or blocking the vascular EGFR 2 pathway." (PMID 35682652, 2022). "ERRFI1 overexpression has been shown to reduce proliferation in GBM cells by binding EGFR to Syntaxin-8 and targeting internalized EGFR to late endosomes for degradation, while knockdown of ERRFI1 expression resulted in increased tumor invasion." (PMID 36231068, 2022). "This instructed CAFs to over-secrete HGF, that activated the MET pathway in tumor cells, thus favoring their escape from MET or EGFR targeting." (PMID 36324182, 2022). "By whole slide learning and computer vision techniques, the percentage of positively stained tumor cells within the tumor areas for EGFR ligands amphiregulin (AREG) and epiregulin (EREG) were found to predict benefit from the anti-EGFR agent panitumumab." (PMID 36011003, 2022). "The current study employs patient-derived tumor organoids (PDTOs) to test the combined inhibition of cGAS-STING and EGFR." (PMID 35992877, 2022). "We have also developed a three-in-one AsiC, targeting EGFR, HER2, and HER3 in one molecule and significantly inhibited tumor growth in xenograft models." (PMID 35142964, 2022). "The expressions of pEGFR, EGFR, pAKT, AKT, pERK1/2, and ERK1/2 protein levels were investigated in tumours from the animals fed with 15% of krill oil." (PMID 35120511, 2022). "In the case of TNBC, nanobodies against tumor-specific antigens such as TNF-α, EGFR, CD3, CTLA-4, STAT-3, AKT2 among others, have been generated and tested for targeting cancer cells." (PMID 36507540, 2022). "Sym013 is a recombinant pan-HER antibody mixture that targets EGFR, HER2, and HER3, effectively suppresses tumor growth, and inhibits the proliferation of cell lines in vitro." (PMID 36551663, 2022). "Detection of tumor type-specific alterations, including AR, ESR1, GNAS, and EGFR alterations in seven samples, as well as EBV, HBV, and MSI positivity in three samples, informed potential tumor origins." (PMID 35486650, 2022). "To date, drugs developed to treat patients with EGFR-vIII or EGFR have proven to be ineffective due to the inability of such drugs to overcome the BBB, to tumor heterogeneity, and to the activation of compensatory pathways such as Src." (PMID 35890294, 2022). "For patients who progress on a first- or second-generation EGFR TKI, the guidelines recommend repeated tumor or liquid biopsy to identify mechanisms of acquired resistance." (PMID 36497340, 2022). "Given the high sensitivity of EGFR-sdCAR T cells against even EGFR-low MCF7 target cells, we were concerned regarding possible on-target off-tumor effects." (PMID 35935988, 2022). "The A/NSCLC patients, one with 38.4% EGFR+ and 45.3% CXCR4+ serum sEVs and the other with 23% EGFR+ and 61.6% CXCR4+ serum sEVs both showed high levels of EGFR and CXCR4 in the primary tumor biopsy." (PMID 35269297, 2022). "A total of 59 patients were excluded due to missing either MGMT methylation, epidermal growth factor receptor amplification, WHO performance status, or planned tumor volume (PTV)." (PMID 35371528, 2022). "The potential of EGFR inhibitors for inducing anti-tumor immunity offers the feasibility of combining the EGFR-targeting therapies, including TKIs and CAR-T with ICIs in EGFR-overexpressed TNBC." (PMID 36612100, 2022). "The current mandatory biomarkers to look for in late-stage NS-NSCLC include different genomic alterations present on EGFR, ALK, ROS1, NTRK, BRAF, MET, and RET, as well as the PD-L1 expression of tumor cells." (PMID 35565387, 2022).
tumor (continued). "While KRAS mutations per se are less frequently observed, GBM shares some common genomic alterations with CRC, like EGFR amplification and WNT activation, which contribute to tumor progression in both primary and recurrent states." (PMID 35664781, 2022). "Thus, using EGFR-targeted DSPE-PEG2000 liposomes as CPT-11 delivery system could improve the therapeutic efficacy of CPT-11 by enhancing the caspase-mediated apoptosis pathway in tumor cells." (PMID 35918704, 2022). "An EGFR small-molecule inhibitor, Gefitinib, can inhibit EGF signaling to destabilize PD-L1 and boost anti-tumor immunity." (PMID 36558902, 2022). "Further mechanistic studies have demonstrated that MIAC directly bind to AQP2 protein, inhibit EREG/EGFR expression and activate downstream pathways PI3K/AKT and MAPK to achieve anti-tumor effects." (PMID 36117171, 2022). "Epidermal growth factor receptor (EGFR) is one of the critical oncogenes and plays a significant role in tumor proliferation and metastasis." (PMID 36613084, 2022). "In the context of tumor cells, it has been observed that CGA can bind to EGFR and inhibit various intracellular cascades, leading to the suppression of cell growth and proliferation." (PMID 36358318, 2022). "Previous studies have found that EGFR/MAPK signaling pathway was directly related to the CRC oncogenic processes and played crucial roles in CRC tumor growth and disease progression." (PMID 35463300, 2022). "AZD9291 is the first novel and irreversible third-generation anti-EGFR agent that shows higher efficacy than other EGFR inhibitors in suppressing GBM cell activity and prolonging the life of mice with orthotopic tumor grafts of GBM." (PMID 35163279, 2022). "To go further, we took advantage of a small cohort of 11 NSCLC patients who had received EGFR‐TKI, and for which paired tumor tissue before treatment and at relapse were available." (PMID 35593080, 2022). "In preclinical studies, co-targeting EGFR and IGF-1R can synergistically enhance the anti-tumor effect of CRC cells." (PMID 35740594, 2022). "Advanced EGFR-mutant patients with strong PD-L1 expressions, defined as Tumor Proportion Score (TPS) ≧50%, have a greater chance of showing de novo resistance to EGFR-TKIs than patients with PD-L1 < 50%22,23." (PMID 35697720, 2022). "Interestingly, recent studies have shown that inhibiting EGFR signalling may reduce tumour cell-intrinsic EGFR-induced programmed death-ligand 1 (PD-L1) upregulation, as well as extrinsic IFNγ-induced signals associated with CD8+ T cell infiltration into the tumour microenvironment (TME)." (PMID 35057796, 2022). "The three patients with best changes in tumor volume demonstrated EGFR and HER2 co-amplification in pretreatment tumor biopsies." (PMID 35264144, 2022). "Compared with anti EGFR mAb or anti c-MET mAb alone, EMB-01 induces significantly stronger anti-tumor activity in PDX and CDX tumor models." (PMID 34025638, 2021). "CRIPTO desensitizes EGFR-mutant NSCLC tumor cells to EGFR-TKI treatment through CRIPTO-mediated Src activation, and inhibition of Src resensitizes CRIPTO-expressing cells to EGFR-TKI treatment." (PMID 34568058, 2021). "EGFR is a tyrosine kinase frequently overexpressed in TNBC and known to be involved in several cancers by promoting tumor growth and migration." (PMID 33995681, 2021). "EGFR, HER2, and HER4 have an effect on tumor cell proliferation and are presumed to be overly expressed in many cancer cells." (PMID 34885957, 2021). "EGFR/B3GNT3 pathway-induced PD-L1 glycosylation leads to inhibition of PD-L1 autophagic degradation, subsequently, facilitates tumor immune escape in a breast xenograft tumor model." (PMID 34493296, 2021).
tumor (continued). "The human epidermal growth factor receptor (HER) family plays pivotal roles in physiologic and pathologic conditions (such as tumor growth, proliferation, and progression in multiple epithelial malignancies)." (PMID 34400948, 2021). "EGFR T790 M was detected in plasma, and MET amplification was found in the tumor at the time of resistance to afatinib." (PMID 34397683, 2021). "Tumor samples showed a statistically significant downregulation of miR-7-5p and upregulation of IRS2 and EGFR, compared to their matched normal tissues." (PMID 34381564, 2021). "SHP2 promoted the tumor cell stemness in EGFR T790M mutant LUAD, and secreted cytokines in the tumor microenvironment (TME) were essential for the stemness regulation and maintenance." (PMID 34217295, 2021). "This analysis indicates that high CD73 expression is associated with a poor response to anti‐EGFR treatment and suggests that high CD73 expression, which potentially could be further induced by the cetuximab treatment, may be involved in the development of tumor resistance during treatment." (PMID 34165921, 2021). "Previously, the fusion of an albumin-binding domain (ABD) to a bivalent anti-EGFR Nb increased BRT and tumor uptake while decreasing renal retention." (PMID 34575943, 2021). "At the present time, international guidelines allow prescription of first-line EGFR-TKI therapy based only on LB in those patients for whom a surgical procedure or biopsy is infeasible, or the amount of tumor tissue is scarce." (PMID 34003366, 2021). "As such, we conducted cost-effective analyses to compare anti-EGFR mAb versus bevacizumab in KRAS, pan-RAS WT patients, and the subgroup of left-sided pan-RAS WT tumor." (PMID 34012917, 2021). "In vitro diagnostics (IVD) tests to detect activating and resistance EGFR mutations in plasma, using allele-specific real-time PCR assays are currently employed and recommended for cfDNA EGFR testing to complement tissue biopsy or as an alternative when tumor tissue is limited or non-accessible." (PMID 33925308, 2021). "In line with this, targeting the pathways closely upstream or downstream of Shc1 (e.g., ErbB2, EGFR, MEK, ERK, PTEN, PI3K) by drugs or molecular manipulation has been shown to enhance anti-tumor immune responses in various studies, as discussed later." (PMID 33807608, 2021). "Previous studies have shown that STAT3 can be activated by both EGFR-dependent and -independent pathways and that STAT3 inhibition can result in tumor growth inhibition and/or apoptosis." (PMID 33809148, 2021). "One of these studies, conducted in xenograft models with BRAF-mutant tumours, showed that treatment with vemurafenib (a specific BRAF inhibitor) was enough to reverse resistance to EGFR inhibitors." (PMID 34359657, 2021). "It demonstrated that the expression of G6PD, EGFR, CHMP6 and PROM2 were elevated in the tumor tissues." (PMID 34885178, 2021). "Within the PDAC tissues and correlated with higher tumor grades, it has commonly been found that IGF1R is highly expressed and co-expressed with EGFR, this is likely to lead to poor survival." (PMID 34360896, 2021). "The mAbs targeting epidermal growth factor receptor (EGFR) and folate receptor have been developed and evaluated for TNBC treatment, but their anti-tumor efficacy is poor in clinical trials." (PMID 34452008, 2021). "To further examine the role of ILT4 in the pathogenesis of EGFR-activated NSCLC, we examined the proliferation and apoptosis of tumor cells upon ILT4 knockdown." (PMID 33537094, 2021). "When EGF activates epidermal growth factor receptor (EGFR), the downstream signaling pathways such as PI3K/AKT and MAPK/ERK can be stimulated, which further confer important roles in metastasis and tumor progression." (PMID 33462201, 2021).
tumor (continued). "The model generated predictions for regional EGFR amplification status (a common and important target in GBM) to resolve the intratumoral genetic heterogeneity across each individual tumor—a key factor for future personalized therapeutic paradigms." (PMID 33594116, 2021). "EGFR-mutant NSCLC cells are addicted to EGFR activity and require this activity to drive tumor growth, survival and metastasis." (PMID 34903832, 2021). "Our results showed that zotarolimus and zotarolimus combined with 5-FU greatly reduced the presence of CD44, EGFR, and TGF-β in tumor immunostaining." (PMID 34361836, 2021). "NGS profiling of CSF circulating tumor DNA is important in NSCLC patients with LM and erotinib plus bevacizumab and chemotherapy is a promising option for patients with LM harboring EGFR C797S/SM." (PMID 34871271, 2021). "We applied CIBERSORT and xCell to calculate the proportion and abundance of tumor-infiltrating immune cells (TICs) in LUAD, and compared the differences in patients with high or low SPP1 expression and wild-type or mutant EGFR." (PMID 34178613, 2021). "MiR-375 inhibits CRC tumour growth, migration and angiogenesis by targeting the CTGF/EGFR-induced downregulation of the PIK3CA-AKT and BRAF-ERK1/2 cascades, thereby acting as a tumour suppressor." (PMID 33865381, 2021). "In order to investigate the anti-tumor activity of anti-EGFR/VEGFR2 BsAb in TNBC cell lines, we assessed the levels of EGFR and VEGFR2 expression in a panel of TNBC cells." (PMID 33804477, 2021). "Surprisingly, in EGFR mutant, TKI resistant humanized NSG immunotherapy model, ILT4 inhibition alone rather than in combination with a PD-L1 inhibitor suppressed tumor growth and immune evasion." (PMID 33537094, 2021). "Well-established markers as therapeutic options in many tumours include the epidermal growth factor receptor (EGFR, ErbB), phosphatidylinositol 3-kinase (PI3K)/Akt/mTOR and Ras/Raf/MAPK." (PMID 33889209, 2021). "Subsequently, the complex signaling network activated via EGFR, such as the PI3K-Akt pathway and RAS/RAF/MEK/MAPK pathway, plays vital roles in several cellular processes, including inhibition of apoptosis, tumor growth, metastasis, and angiogenesis." (PMID 33522929, 2021). "Gene amplification (e.g., EGFR, TERT, MYC, and ERBB2) was identified in tumor samples from 10 patients but was present only in paired tumors for one patient." (PMID 34109114, 2021). "Some of these ADC targets are known oncoproteins, such as EGFR (targeted by two ADCs), HER-2, c-MET, Trop-2 or tumor antigens, such as tissue factor (CD142) and B7-H3, the latter being recently validated as a novel immune-checkpoint." (PMID 34206707, 2021). "MLN4924 was found to trigger epidermal growth factor receptor (EGFR) dimerization and activate EGFR downstream signaling pathways such as RAS/RAF/MEK/ERK and PI3K/AKT1/mTOR promoting tumor sphere formation and inducing wound healing in mouse models." (PMID 33572115, 2021). "We further characterized and compared the pathological features of the CDX versus PDX tumor using H&E and immunohistochemistry staining against Ki67, ER, PR, HER2, and EGFR." (PMID 34145270, 2021). "In this in vitro model, CAFs affect proliferation; EGFR expression; and, to some extent, the EMT and cancer stem cell phenotype of HNSCC tumor cells." (PMID 34283070, 2021). "The literature also demonstrates the ability of EGFR inhibitors to increase MHC expression and antigen presentation on tumor cells." (PMID 33485341, 2021). "In this investigation, we have generated a tetravalent anti-EGFR/VEGFR2 BsAb with IgG-like format, which has ability to simultaneously block EGFR and VEGFR2 signaling pathways and demonstrate superior anti-tumor activity in vitro and in vivo models on TNBC." (PMID 33804477, 2021). "These works indicated that metallic nanoparticles, such as McAb or EGFR-KTI deliveries, extended the application of metallic nanoparticles in targeting therapy for tumor." (PMID 34322025, 2021).
tumor (continued). "Our findings reveal EGFR/ERBB inhibitor-stimulated influx of T cells into orthotopic B4B8 tumors propagated in syngeneic mice and reduced anti-tumor activity of AZD8931 on tumors propagated in immune-deficient mice." (PMID 33485341, 2021). "Having found changes in tumor uptake of 89Zr-radiolabeled antibodies after treatment with cetuximab or with INC280 and trametinib, we next investigated changes in MET, EGFR, and HER2 protein levels at the cellular level." (PMID 32646879, 2021). "In prior studies, patients with left-sided tumours receiving chemotherapy plus an anti-EGFR antibody have demonstrated superior treatment outcomes in terms of PFS, OS, and ORR compared with patients with right-sided tumours receiving the same therapy." (PMID 33928486, 2021). "JAK2/STAT3, a critical signaling pathway in tumorigenesis, is mediated through EGFR signaling; STAT3 can act as a transcription factor for tumor progression." (PMID 33805840, 2021). "The mechanism was that YTHDF2 acted as a tumor suppressor and bound the m6A modification site of EGFR 3'-UTR, thus promoting the EGFR mRNA degradation." (PMID 34345203, 2021). "Studies have shown that epidermal growth factor receptor-CAR (EGFR-CAR) lentivirus-infected T cells have a robust specific inhibitory effect on the growth of TNBC cells and tumor occurrence in vitro and in vivo." (PMID 35111680, 2021). "We compared the changes in tumor infiltration levels of CD4, CD8, or Foxp3‐positive T cells in tumor tissues before and after EGFR‐TKI treatment, in the patients who developed EGFR‐TKI resistance." (PMID 33305905, 2021). "DLL4-Notch signaling pathway interacts with several molecules and other signaling pathways, including PI3k, EGFR, and MMP9, all related to tumor invasion, proliferation, and metastasis." (PMID 36643842, 2021). "The LCP EGFR siRNA+PDT group of SCC4 and SAS tumor volumes were reduced by ~205% and ~220%, respectively, compared to the PBS group." (PMID 34575510, 2021). "We subsequently assessed the anti-tumor responses of co-targeting Notch signaling that maintains MEC stem-like cells and EGFR signaling downstream of the CRTC1-MAML2 oncogenic fusion in MEC." (PMID 33473104, 2021). "The combination of anti-EGFR and anti-VEGF was found to have anti-tumor activity through the regulation of the ARK and ERK signaling pathways." (PMID 34575959, 2021). "Bi‐EGF‐IT exhibited a comparable potency to that of the FDA‐approved EGFR inhibitor, erlotinib, for inhibiting HNSCC tumor growth in vivo using both subcutaneous and orthotopic HNSCC xenograft mouse models." (PMID 33540470, 2021). "Various stages of tumor metastasis need upregulation of matrix metalloproteinases (MMPs), adhesion molecules, EGF, EGF receptor (EGFR), and vascular endothelial growth factor." (PMID 33922139, 2021). "Antibodies and targeting ligands, such as folic acid, epidermal growth factor receptor I (EGFR), and RGD, have been conjugated to AuNPs for targeted tumor imaging or chemotherapy drug delivery." (PMID 33920453, 2021). "EGFR is significantly altered in OSCC and its prolonged signaling is mitogenic, driving uncontrolled proliferation of tumor cells." (PMID 33889303, 2021). "EGFR has been proposed to be the prognostic marker for HNSCC that closely related with radiation sensitivity, tumor size and recurrence." (PMID 34986125, 2021). "The adaptive immune response is reportedly involved in tumor regression mediated by tumor-targeted therapies, such as anti-HER2/neu antibody therapy and EGFR TKI." (PMID 33954115, 2021). "To explore a suitable treatment method for EGFR C797S-mediated TKI resistance, we examined the effects of quercetin and brigatinib on tumor growth in vivo." (PMID 34572484, 2021).